EP300 (EP300 lysine acetyltransferase)
Diseases named in the same sentence as EP300 in open-access papers (continued):
Sharing a sentence is not in itself a finding about the gene and the disease.
breast carcinoma (continued). "A recent report proposed that SETD5 regulates glycolysis through the regulation of EP300/HIF-1a co-activators upon the hypoxic condition in breast cancer stem-like cells." (PMID 37264456, 2023). "Further, we use this potent and selective inhibitor to provide insight into the role of CREBBP/EP300 in defining the transcriptional programs and chromatin landscape of ER+ breast cancer." (PMID 35353838, 2022). "CREBBP/EP300 HAT inhibition suppresses EGR-dependent transcription in breast cancer in vitro and in vivo." (PMID 35804935, 2022). "Other genes associating with this component were CHD3 in bladder cancer, HERC2 in ovary cancer, PIK3C2B in lung squamous cell cancer, EP300 in skin cancer (and breast cancer at a FDR of 2%), RBBP5 in pan-cancer, and SMC1B in pan-cancer." (PMID 35764656, 2022). "Using the potent and selective inhibitor CPI-1612, we show that CREBBP/EP300 acetyltransferase inhibition potently suppresses in vitro and in vivo growth of breast cancer cell line models and acts in a manner orthogonal to directly targeting ER." (PMID 35353838, 2022). "To investigate the anti-tumor effects of CREBBP/EP300 HAT inhibition in ER+ breast cancer in vivo, we used an MCF7 xenograft model." (PMID 35353838, 2022). "To better understand how CREBBP/EP300 HAT inhibition leads to transcriptional changes in ER+ breast cancer cells, we performed ATAC-seq and H3K27 acetyl ChIP-seq upon treatment of MCF7 cells with CPI-1612." (PMID 35353838, 2022). "As another major component of the complex, EP300 (also termed as KAT3B or p300) is predictive of worse prognosis in human malignancies, such as prostate, liver, kidney, and breast cancer." (PMID 34544413, 2021). "We have previously determined that EP300 regulates drug resistance and tumor initiation capabilities in breast cancer cells." (PMID 33417085, 2021). "Large breast cancer gene expression data sets revealed that EP300 expression is positively correlated with the expression of CSC markers and poor prognosis in TNBC and basal-like BC." (PMID 33167919, 2020). "The association between EP300 expression and RFS was assessed in 6234 breast cancer patients, of which 198 TNBC cases were available for analysis." (PMID 33167919, 2020). "EP300 gene expression in large published breast cancer data sets positively corresponded with genes and molecular pathways associated with CSC function and predicted poor RFS in TNBC and basal-like BC." (PMID 33167919, 2020). "BRG1, an active subunit of the SWI/SNF chromatin-remodeling complex, enables the EP300-dependent transcription of proliferation and DNA repair genes from their E2F/CpG-driven promoters in breast cancer cells." (PMID 31614656, 2019). "In this study, PARP1 was shown to be an active component of the transcription machinery that drives BRG1-EP300-dependent gene expression by the poly-ADP-ribosylation of EP300 in breast cancer cells." (PMID 31614656, 2019). "Together, these results suggest a significant role of EP300-mediated acetylation of FOXO3 in regulating HER2-positive breast cancer cell survival and their lapatinib sensitivity." (PMID 31357743, 2019). "In summary, in the present study we identify a role of EP300-mediated FOXO3 acetylation in the regulation of lapatinib sensitivity in breast cancer." (PMID 31357743, 2019). "Lastly, we have unveiled that EP300 is downregulated in metaplastic breast cancer, a rare aggressive form of the disease with histological evidence of EMT and poor clinical outcome." (PMID 28341962, 2017). "Immunohistochemical analysis demonstrated that EP300 expression was low in metaplastic breast cancer, a rare, but aggressive form of the disease with poor prognosis that is characterized by morphological and physiological features of EMT." (PMID 28341962, 2017). "Some genes in this signature were also validated in a previously generated EP300-depleted model of breast cancer using minimally transformed mammary epithelial cells." (PMID 28341962, 2017).
breast carcinoma (continued). "EP300 silencing is also associated with increased in vitro tumorigenicity and CSC-like markers, whilst its ectopic expression in basal-like breast cancer cells partly rescues the epithelial, differentiated and paclitaxel-sensitive phenotype." (PMID 28341962, 2017). "Eight (47%) metaplastic breast cancers were histologically heterogeneous, mainly with the nests of squamous differentiation showing positivity for both E-cadherin and EP300." (PMID 28341962, 2017). "We have previously shown that in a minimally transformed cellular model of breast cancer, experimental downregulation of EP300 decreases paclitaxel sensitivity and leads to the generation of paclitaxel-resistant cells." (PMID 28341962, 2017). "In order to study how breast cancer epithelial cells respond to EP300 downregulation, we generated stably transfected MCF-7 cells with a lentivirus driving the expression of hairpins targeting EP300 mRNA." (PMID 28341962, 2017). "“Associations of genetic variants in the estrogen receptor coactivators PPARGC1A, PPARGC1B and EP300 with familial breast cancer”." (PMID 23216862, 2012). "In addition, CBP/EP300 also activates transcription of the androgen receptor (AR) and thus promotes AR signaling in AR-positive breast cancer model MDA-MB-453 in vitro and in vivo." (PMID 40165290, 2025). "Notably, A485 exposure has also demonstrated the ability to downregulate estrogen receptor protein levels in breast cancer, and EP300/CREBBP acetyltransferase inhibition curtails estrogen signaling through FOXA1-bound enhancers." (PMID 38564048, 2024). "However, large breast cancer gene expression datasets revealed that histone acetyltransferases EP300 was correlated with the cancer stem cells and poor prognosis in triple negative breast cancer and basal-like Breast cancers." (PMID 37876590, 2023). "Thus, while CREBBP/EP300 HAT inhibition globally reduces H3K27 acetylation in ER+ breast cancer cells, changes in chromatin accessibility are much more circumscribed." (PMID 35353838, 2022). "EP300 was a tumor suppressor, down-regulated in metaplastic breast cancer." (PMID 36258162, 2022). "ESR1, FOXA1, GATA3, and EP300 TFBSs were enriched in CCVs for overall breast cancer." (PMID 34439109, 2021). "The results demonstrated that high EP300 RNA expression might function as prognostic marker for poor RFS in TNBC/basal-like breast cancer." (PMID 33167919, 2020). "Interestingly, some researchers observed EP300 cytoplasmic location in cancer cells such as breast cancer and osteosarcoma cells 24, 25, but in our study here, EP300 protein showed strong nuclear staining in ESCC." (PMID 31632486, 2019). "EP300 expression was analysed by immunohistochemistry in 17 samples of metaplastic breast cancer." (PMID 28341962, 2017). "In the breast cancer core network, we found Fibronectin 1 (FN1), which is related to migration; FLT4 involved in angiogenesis; GSK3B, an anti-proliferative enzyme; KPNA2, a nucleopore transporter and the EP300-associated transcriptional activator NCOA3." (PMID 28775339, 2017). "EP300 plays a major role in the reprogramming events, leading to a more malignant phenotype with the acquisition of drug resistance and cell plasticity, a characteristic of metaplastic breast cancer." (PMID 28341962, 2017). "Finally, immunohistochemical analysis reveals a strong downregulation of EP300 in metaplastic breast cancer, a rare, but aggressive form of invasive breast cancer with histological evidence of EMT, which has a poor clinical outcome." (PMID 28341962, 2017). "We tested this on the breast cancer cell line MCF7 for which sequence data from both input material as well as multiple ChIPseq experiments for a number of DNA-associated proteins (ER, EGR1, GATA3, CTCF, MAX, and EP300) are available." (PMID 25887352, 2015). "Interestingly, EP300, which acts as a histone acetyltransferase to activate gene transcription, has been previously reported to exert an anti-cancer function in tumors like breast cancer." (PMID 32943995, 2020).
breast carcinoma (continued). "The fact that at least some of them were previously confirmed to be enriched in BRG1–EP300 functional complexes prompted us to check if EP300 interacted with PARP1 and if any of BRG1–EP300 components could undergo ADP-ribosylation in proliferating breast cancer cells." (PMID 31614656, 2019). "All three microRNAs were upregulated and repressed NEDD4L, EP300, and SMAD7 in breast cancer, influencing epithelial–mesenchymal transition, tumoral transformation, and therapy response." (PMID 40943553, 2025). "These included several well-known cancer genes or their family members with previously less recognized role in breast cancer—FGFR3, FGFR4, NOTCH3, KMT2B, EP300, FLT4 and FAT1." (PMID 40858906, 2025). "For instance, the LIM protein Ajuba plays a crucial role in breast cancer by recruiting deleted in breast cancer-1 (DBC1; also known as CCAR2 or p30DBC) and transcriptional coactivators EP300/CBP to form a tertiary complex." (PMID 38914477, 2024). "We noted that GI50 values for CPI-1612 were similar for ER positive breast cancer cell lines in both culture conditions, demonstrating that CREBBP/EP300 inhibition can directly impact hormone-driven proliferation." (PMID 35353838, 2022). "In this study we show that CREBBP/EP300 HAT inhibition with the potent and selective inhibitor CPI-1612 can inhibit the growth of breast cancer cell lines in vitro and impede tumorigenesis in vivo at well tolerated doses with demonstrated target engagement." (PMID 35353838, 2022). "Moreover, high expression and activity of EP300 was demonstrated to be associated with various diseases and malignancies, including pulmonary fibrosis, nasopharyngeal carcinoma (NPC), hepatocellular carcinoma (HCC), non-small cell lung cancers (NSCLC), prostate cancer (PCa), and breast cancer (BC)." (PMID 36076918, 2022). "Given the known functional link between CREBBP/EP300 and ER signaling, we further explored the impact of CPI-1612 in the context of ER+ breast cancer." (PMID 35353838, 2022). "The data presented here is to our knowledge the first study describing a context-depended oncogenic role of EP300 in CSC phenotype in TNBC and basal-like breast cancer." (PMID 33167919, 2020). "Collectively these data demonstrated a novel oncogenic role for EP300 in TNBC and basal-like breast cancer biology." (PMID 33167919, 2020). "In breast cancer, GREB1 functions as a coactivator through binding to ER and recruitment of the EP300/CBP complex to ER target genes." (PMID 30644358, 2019). "We found that specific genes such as CBL, RHOA, EP300, RAC1, CDK1, and CDH1 are involved in the migration and invasion of breast cancer." (PMID 30930932, 2019). "Triple-negative, basal-like breast cancer cells show many mesenchymal characteristics and thus we generated stably transfected cells derived from CAL51 and MDA-MB-231 in which EP300 was upregulated after transfection with an expression vector." (PMID 28341962, 2017). "KAT2B, EP300, KAT6A (MYST family), and KAT2A (GNAT family) are recruited to ER-responsive promoters and are critical for estrogen-dependent proliferation of ER-positive breast cancer cells." (PMID 40165290, 2025). "However, dependence on the acetyltransferase activity of CREBBP/EP300 in ER+ breast cancer is consistent with the known physical and functional links between CREBBP/EP300 and ER and has been corroborated in another recently published study." (PMID 35353838, 2022). "Given the functional link between CREBBP/EP300 and ER, we investigated whether inhibition of CREBBP/EP300 acetyltransferase activity would impact the viability of ER+ breast cancer cell lines." (PMID 35353838, 2022). "Interestingly, in an unrelated breast cancer cell line, MCF7 expression of GATA6 also decreased upon EP300 knockdown." (PMID 35536676, 2022). "In addition to EP300, GCN5 is another family member of HATs that was found to play a key role in the TGF-β/SMAD signaling pathway in breast cancer cells." (PMID 36076918, 2022).
breast carcinoma (continued). "Therefore, FOXO3 acetylation, regulated coordinately by EP300 and sirtuins, is an important PTM which regulates FOXO3 expression and transcriptional activity to modulate lapatinib sensitivity in breast cancer." (PMID 31357743, 2019). "We analysed 17 metaplastic breast cancer samples that all scored negative or low for E-cadherin expression (scores 0 or 1) and found that all of them also scored low (score 1) for EP300 expression in the mesenchymal metaplastic component." (PMID 28341962, 2017). "Upregulation of these miRs, found in aggressive basal-like, oestrogen receptor-negative, grade 3 breast cancers and drug-resistant cell models, leads to a downregulation of EP300 and E-cadherin with initiation of an EMT." (PMID 28341962, 2017). "Though a few early studies identified low frequency EP300 mutations in colorectal carcinoma, breast cancer, and gastric cancer, the full spectrum of mutational inactivation of CREBBP and EP300 would not be fully evident until the genomics era." (PMID 24622842, 2014). "Furthermore, we revealed that SIRT1 deficiency is associated with substantial induction of acetylated markers on six breast cancer-related gene promoters: AR, BRCA1, ERS1, ERS2, EZH2, and EP300, suggesting an active role of SIRT1 in regulating the expression of these genes in BC." (PMID 30380732, 2018). "Lower levels of EP300 and higher levels of the nuclear deacetylases, sirtuins (e.g., SIRT1 and SIRT6) were also detected in the BT474-LapR cells, which might also contribute to the reduced FOXO3 activity in BT474-LapR cells and therefore lapatinib resistance in HER2-positive breast cancer cells." (PMID 31357743, 2019). "Currently, no HAT inhibitors are being tested in clinics for breast cancer specifically, but novel inhibitors such as those targeting CBP/EP300 BRD recently entered early clinical trials for solid tumor treatment." (PMID 40165290, 2025). "FOXA1, together with EP300 and RUNX1, regulates the expression of E-cadherin, and is expressed in luminal, but absent in triple-negative and basal-like breast cancers." (PMID 33417085, 2021). "We further demonstrate that CREBBP/EP300 HAT inhibition acts in an overlapping but nonidentical manner to the standard of care Fulvestrant, supporting its potential development in combination or resistance settings in ER+ breast cancer." (PMID 35353838, 2022). "Importantly, metaplastic breast cancer is enriched in the markers of CSCs and EMT and we show here low EP300 expression when compared to non-cancerous breast epithelium." (PMID 28341962, 2017).
prostate carcinoma (101 papers, 2011 to 2025). A carcinoma that arises from epithelial cells of the prostate gland. "In panCancer analyses anti-tumor immune activity was increased in EP300 mutated esophageal, stomach and prostate cancers." (PMID 32523042, 2020). "One key mutated gene in these pathways is EP300, a crucial gene for prostate cancer cell proliferation and hormone responsiveness of AR." (PMID 25915538, 2015). "Besides HNSCC, upregulation of cytolytic activity significantly correlated with EP300 mutation in esophageal squamous cell carcinomas, gastric carcinomas and prostate carcinomas." (PMID 32523042, 2020). "Antagonizing nuclear or transcription factors has been efficacious in recent examples, as inhibitors against EP300, an AR interacting protein, were efficacious in prostate cancer models." (PMID 35550030, 2022). "This study investigated the role of EP300/CREBBP inhibitors in enzalutamide-resistant prostate cancer." (PMID 33705753, 2021). "EP300 expression also contributes to the growth of prostate cancer and is a predictor of aggressive characteristics of this cancer." (PMID 34149798, 2021). "It has been shown that EP300 is upregulated by androgen ablation, and its expression correlates with worse prognosis in prostate cancer." (PMID 27916838, 2016). "Similarly, EP300 and CREBBP have been implicated in prostate cancer, with the former identified as an oncogene in a significant proportion of tumors." (PMID 38002524, 2023). "Furthermore it includes two pulmonary adenocarcinoma cell lines A549 and HCC515 as well as one prostate carcinoma cell line (PC3) with relative downregulation of EP300 expression." (PMID 32523042, 2020). "A recent study reported A-485, a new inhibitor selectively targeting histone acetyltransferase (HAT) domain of EP300/CREBBP, showed antitumor effects in several hematologic malignancies and prostate cancer." (PMID 38693103, 2024). "miR-574-3p can suppress target genes, as RAC1 and EP300 both identified its role in stimulating VEGF-mediated angiogenesis, and genistein used to treat prostate cancer can upregulate miRNA-574-3p and thus be used to treat cancer." (PMID 37298699, 2023). "The histone acetyltransferases EP300 and CREBBP are involved in regulation of cellular events in advanced prostate cancer." (PMID 33705753, 2021). "Overall, these data are consistent with the significant correlation found between the combined gene expression of GPX2, EP300, and PSMB2, and OS in prostate cancer patients." (PMID 32933107, 2020). "Then, we evaluated the gene expression profiles for the six HUB nodes (ABL1, EP300, FYN, MYC, PSMB2, and SRPK2) in all the prostate cancer cells, compared to normal prostate EPN cells." (PMID 32933107, 2020). "The two related EP300 inhibitors NK13650A and NK13650B impair the viability of prostate cancer cells when given at high concentrations." (PMID 28486411, 2017). "The dual, allosteric activator of EP300 and CREBBP I-CBP112 increases histone acetylation, mainly at H3K18, and impairs prostate cancer cell proliferation when applied at a low micromolar concentration." (PMID 28486411, 2017). "We observed a similar effect of I-CBP112, which targets the CBP/EP300 bromodomain, on the mitotic division in a culture of MDA-MB-231, whereas a substantial reduction in c-MYC, which is considered a TNBC driver, was observed in prostate cancer." (PMID 34572840, 2021).
prostate carcinoma (continued). "Recently, high levels of EP300 were correlated to both prostate cancer progression and chemotherapy resistance in metastatic CRPC patients, and it has emerged as a possible co-target in chemo-resistant prostate cancer treatment." (PMID 32933107, 2020). "EP300 and CREBBP, regulated by way of miR-30a and CREB1, are highly related transcriptional co-activators possessing histone acetyltransferase activity and were known to be involved in the survival and invasion pathways of prostate cancer." (PMID 23282077, 2012). "G-profiler does not identify EP300 as a gene involved in prostate cancer as it is done by DAVID." (PMID 22518120, 2012).